CCND1 (cyclin D1)
Diseases named in the same sentence as CCND1 in open-access papers (continued):
Sharing a sentence is not in itself a finding about the gene and the disease.
breast cancer (continued). "For breast cancer, HER2-enriched specific amplification of ERBB2, basal-specific amplification of CCNE1, and luminal B specific amplification of CCND1 were remarkably salient in both TCGA and METABRIC data." (PMID 30885118, 2019). "More studies with a larger sample size are warranted to further examine how the different molecular subtypes of breast cancer affect the interaction of BRCA1 and CCND1 with T cell activation in patient survival." (PMID 31023256, 2019). "Further reported CASC9 target genes were CDK4, CyclinD1 (CCND1), E-Cadherin (CDH1) and BCL2 in lung adenocarcinoma, ESCC cells, oral squamous cell carcinoma and in breast cancer." (PMID 31412811, 2019). "Activation of cyclin D1 and CDK4/6 plays a significant role in the tumorigenesis of HR+/HER2+ breast cancer." (PMID 30018827, 2018). "Cyclin D1, p-CDK4, and p-Rb exhibit a concerted upregulation in the LEM4 overexpressing ER+ breast cancer cells." (PMID 30301939, 2018). "The results demonstrated that the expression of ZEB1 was positively correlated with those of Bcl-xL and cyclin D1, highlighting that increased expression of ZEB1 contributes to the cellular mechanisms that mediate breast cancer chemoresistance." (PMID 29352223, 2018). "To gauge the confounding nature of commonly amplified genes in breast cancer, we further performed multivariate analysis on the candidate genes with cases of amplification of MYC, FGFR1, CCND1, and ERBB2." (PMID 30181556, 2018). "For example, troglitazone induced G1 arrest and apoptosis by reducing the expression of cyclin D1 and CDK6 in breast cancer cells." (PMID 30018246, 2018). "Our results showed that PIP5Kα is necessary for breast cancer cell proliferation, as evidenced by the increases in the cell proliferation markers E2F1, CDK1 and CCND1 and the decrease in the tumour suppressor FOXO3." (PMID 29851245, 2018). "Altogether, these results further reveal that both CCND1 and PGR are involved in mediating the anti-breast cancer effects of TAM in ER+-breast cancer tissue." (PMID 29416786, 2018). "TIPE2 suppresses the proliferation and tumorigenesis by inhibiting β-catenin, cyclin D1 and c-Myc, and metastasis via AKT and p38 signaling pathways in breast cancer." (PMID 30157801, 2018). "In addition, CDK4/cyclin D inhibition may be additionally beneficial for the treatment of human epidermal growth factor receptor 2 (HER2) and RAS‐driven breast cancers and potentially many other cancers because cyclin D1 displays most frequent somatic copy number aberrations of all cancer genes." (PMID 29669860, 2018). "MiR-30a-5p overexpression inhibits breast cancer cell proliferation by downregulating UBE3C, as well as cyclin B1, cyclin D1, and c-myc." (PMID 30158978, 2018). "Previous study showed that overexpression of Gologh3 in 7 kinds of breast cancers promoted the proliferation with the downregulation of cyclin-dependent kinase (CDK) inhibitor p21Cip1 and upregulated the CDK regulator cyclin D1." (PMID 29534690, 2018). "We next examined the expression of three estrogen-responsive genes in these two cell lines; namely Growth Regulation By Estrogen In Breast Cancer 1 (GREB1), Cyclin D1 (CCND1) and Trefoil Factor 1 (TTF1)." (PMID 30370249, 2018). "Recently, PRMT2 levels were found to be decreased in breast cancer cells, while knockdown of PRMT2 correlated with increased expression of both p21 and cyclin D1 indicating a regulatory role for PRMT2 in cell cycle progression." (PMID 29568320, 2018). "First, we found that incubation of cells with different concentrations of EphrinA1 decreased the levels of EphA2, and CCND1 and c-MYC, consistent with previous reports showing an inverse correlation between EphA2 level and EphrinA1 in breast cancer cells." (PMID 30451837, 2018). "PTPRN2, MERTK, TNC and SOX4 were identified to be targets of miR-335, AIB1 and CCND1 were the targets of miR-17-5p, and H-RAS and HMGA2 were verified as targets of let-7 in breast cancer." (PMID 30309377, 2018).
breast cancer (continued). "For this purpose, we considered breast cancers, where amplifications of ERBB2 (Chromosome 17), CCND1 (Chromosome 11) and MYC (Chromosome 8) oncogenes are frequently observed (∼15%, 11% and 38%, respectively in the TCGA cohort)." (PMID 29069713, 2017). "The region contains CCND1 and other potential oncogenes such as FGF3, FGF4 and MYEOV and there is good evidence that this region is relevant to breast cancer." (PMID 28095868, 2017). "The results of the research by Goel S indicated that the complex of cyclin D1 and CDK4 played important roles in the resistance of HER2-positive breast cancer cells to the anti-HER2 therapy." (PMID 28438180, 2017). "Our data supports previous gene-candidate approaches that have shown expression of the oncogene Cyclin D1 requires H2A.Z acetylation at enhancer and promoter elements in ER positive MCF-736 and ER-negative MDA-MB23137 breast cancer cell lines." (PMID 29116202, 2017). "The effect of copy number gains of known oncogenes such as ERBB2, CCND1 and C-MYC in breast cancer, was used to assess the robustness of the platform." (PMID 28697743, 2017). "The critical role of cyclin D1 for MAPK-mediated oncogenesis was established first in the murine model for skin cancer and later for breast cancer." (PMID 28474232, 2017). "At present, it is known that Cks1 overexpression can occur due to gene amplification in breast cancer and myeloma, and CKS1 is a transcriptional target of c-Myc, B-RAF, and cyclin D1." (PMID 29383129, 2017). "PIK3CA‐H1047R mammary tumors showed strong activation of phosphorylated AKT, phosphorylated Gsk3‐β, cyclin D1, and activated β‐catenin compared to tumors from Her‐2 transgenic mice." (PMID 28296140, 2017). "We demonstrated that the drivers showed significant attributes of cancer genes, and significantly overlapped with known cancer genes, including MYC, CCND1 and ERBB2 in breast cancer, and the lncRNA PVT1 in multiple cancer types." (PMID 28719033, 2017). "At the gene levels, genes with recurrent amplifications in breast cancer showed different degrees of concordance: 100% for ERBB2 and FGFR1, 96% for CCND1, but 88% for MYC, suggesting possible differences for driver genes." (PMID 27028851, 2016). "Both Cyclin D1 and ZNF703 were among the genes identified as breast cancer drivers, as were an additional 27 genes with E2-induced R-loops." (PMID 27552054, 2016). "It turned out that, the protein levels of β-catenin, Snail, Axin 2 and Cyclin D1 in the carcinoma tissue (C) were elevated along with MUC16 in the number 1 and number 2 breast cancer samples, compared with the counterparts of normal tissue (N)." (PMID 27167110, 2016). "MST3 induces cyclin D1 by binding VAV2 and enhancing Rac1 activation to promote the tumorigenicity of breast cancer." (PMID 26910843, 2016). "We then focused the comparison of CNAs on known driver oncogenes located within regions frequently amplified in breast cancer: ERBB2 (17q12), CCND1 (11q13.3), FGFR1 (8p11.23), MYC (8q24), and PAK1 (11q14.1)." (PMID 27028851, 2016). "This cluster was found to be deleted in 17% of ovarian cancers, 20% of melanomas, and 22% of breast cancers; for example, miR-17-5p has tumor suppressor role in breast cancer by repressing the expression of AIBI and Cyclin D1." (PMID 27127675, 2016). "Decreased cyclin D1 and cyclin D1-CDK4/6 kinase activity reduces invasion and migration in breast cancer cells." (PMID 27191497, 2016). "In summary, NLN expression was directly regulated by miR-193a-5p, and CCND1, PLAU, and SEPN1 expression was directly regulated by miR-193a-3p in breast cancer cells." (PMID 27307030, 2016).
breast cancer (continued). "The oncogenetic tree model was built on CNV of ErbB2, AKT2, KRAS, PIK3CA, PTEN, and CCND1 genes in 963 cases of tumors with sequencing and CNA data of human breast cancer from TCGA." (PMID 27190992, 2016). "Numerous lines of evidence point to an important role of a dysregulated cyclin D1:CDK4/6 complex in both the initiation and progression of many cancers, including breast cancer." (PMID 26857361, 2016). "Knockdown of CCND1, PLAU, SEPN1, and NLN suppressed cell growth, similar to miR-193a-5p and miR-193a-3p overexpression in breast cancer cells." (PMID 27307030, 2016). "In human breast cancer MDA-MB-231 cells, (−)-oleocanthal induces G1/M arrest by modulating the expression of CDK6, cyclin D1, p21, and p27 and induces cell apoptosis by activating the caspase pathway." (PMID 27259268, 2016). "This is consistent with our data, which showed that wild-type PES1 upregulated the expression of cyclin D1 through maintaining the stability of ERα, and consequently, PES1 positively affected the cell cycle progress and the growth of breast cancer cells." (PMID 27409667, 2016). "Furthermore, previous association studies have identified susceptibility alleles for breast cancer in two genes, TGFBR2 (transforming growth factor beta receptor II) and CCND1 (cyclin D1), which may be involved in immune regulation in cancer patients, including those with breast cancer." (PMID 26621531, 2016). "A number of the identified CD47-dependent genes including MBP1, TBL1XR1, girdin, cyclin D1, CDC27, SPAG9, and JAK1 have reported functions in breast cancer progression." (PMID 26840086, 2016). "Recent studies have demonstrated that CCND1 activation can induce EMT in tumor cells, such as ovarian cancer, breast cancer, esophageal cancer and epidermoid carcinoma cells." (PMID 27409796, 2016). "Knockdown of miR-27b augmented Nischarin (NISCH) and suppressor of tumorigenicity 14 (ST14) expression in human breast cancer, down-regulated STAT3, c-myc and cyclin D1 in glioma." (PMID 26910911, 2016). "Frequently altered genes in breast cancer can be useful as clinical markers, such as HER2 or CCND1, which allows the identification of the clonal relationship in a tumour pair." (PMID 26452468, 2015). "Treatment of breast cancer cells with leptin exhibited striking increase in MTA1, Wnt1, β-catenin and cyclin D1 expression in comparison to untreated cells." (PMID 26036628, 2015). "In the present study, we investigated the effects of short-term administration of a high-dose of atorvastatin on the conventional breast cancer pathological markers ER, PR, HER2, as well as the cell cycle regulators cyclin D1 and p27." (PMID 25925673, 2015). "In breast cancer, DACH1 has been shown to repress CXCL8 through blocking activation from AP1 and NF- kappaB binding sites and inhibit cyclin D1 transcription though AP-1/CREB." (PMID 25788272, 2015). "Interestingly, cyclin D1 expression and Akt phosphorylation were significantly lower in the Wnt1 knockdown groups, suggesting that Wnt/β-catenin signaling may positively regulate breast cancer growth through activation of the cyclin D1 and Akt signaling pathways." (PMID 26202299, 2015). "AIMs have also been shown to decrease cyclin D1 (an NF-κB target gene) and increase CDKN1A (p21) levels in cultured breast cancer cells." (PMID 25897966, 2015). "Over-expression of twist induced cell proliferation through Cyclin D1 up-regulation which in turn increased the tumorigenic property of MCF-7 cells, indicating the involvement of twist in breast cancer progression." (PMID 26491966, 2015). "Remarkably the combined analysis of MYC, HER2, CCND1 and PTEN aberrations suggested that aberrations of multiple PTEN/AKT pathway genes have a strong additive effect on breast cancer prognosis." (PMID 26672755, 2015).
breast cancer (continued). "In this study, we further verified ophiobolin O-induced G1 phase arrest in human breast cancer MCF-7 cells, and found that ophiobolin O reduced the phosphorylation level of AKT and GSK3β, and induced down-regulation of cyclin D1." (PMID 25603341, 2015). "This was further verified by Western analysis in the MMTV-Ron VDR−/− mammary tumors showing enhanced active β-catenin (ABC) expression, correlating with higher protein levels of c-Myc and Cyclin D1." (PMID 26008979, 2015). "Assessment of cyclin D1, FOXP1, NRP1 and CD99 expression was repeated on a validation cohort of 82 BRCA1 and 65 sporadic basal-like breast cancers." (PMID 26152113, 2015). "Our results are also interesting in light of a previous study showing that PTK6 promotes p38 MAPK activation, subsequent Cyclin D1 expression and migration in the context of heregulin- or EGF-stimulated breast cancer cells." (PMID 26084280, 2015). "In ovarian and breast cancer, reexpression of ARH1 inhibits cancer cell growth in vitro and in vivo, induces p21WAF1 and downregulates cyclin D1 promoter activity." (PMID 24747418, 2014). "Furthermore, overexpression of AGK enhanced G1-S phase transition in breast cancer cells, which was associated with activation of AKT, suppression of FOXO1 transactivity, downregulation of cyclin-dependent kinase inhibitors p21Cip1 and p27Kip1 and upregulation of the cell cycle regulator cyclin D1." (PMID 24886245, 2014). "Meanwhile, upregulation of miR-195 expression has been shown to suppress cell proliferation and invasion by targeting the Raf-1 and Ccnd1 genes in both ZR-75-30 and MCF7 human breast cancer cells." (PMID 24402230, 2014). "Studies in breast cancer cell lines had already shown that PHD1 is oestrogen inducible and in Drosophila, it was shown that there is a genetic interaction between cyclin D1 and PHD1." (PMID 24858415, 2014). "The CCND1, CCNB1, and STAT1 genes neighboring BRCA1 have also been reported to have important roles in breast cancer recurrence." (PMID 24497942, 2014). "The chimeric CCND1-TROP2 mRNA, which independently translates both the cyclin D1 and TROP2 proteins, was isolated from human ovarian and mammary cancer cells and was found to be expressed in gastrointestinal, ovarian and endometrial tumors." (PMID 25176350, 2014). "The present data also suggested that BrMC-mediated inhibition of cyclin D1 is directly proportional to the suppression of HER-2/neu and PI3K/Akt in human breast cancer cells." (PMID 24765191, 2014). "SPA treatment also caused a significant reduction in EGF-induced cell cycle progression, which was accompanied by the reduced expression of cyclin D1 and CDK4 and a corresponding increase in p21 and p27 levels in MDA-MB-231 breast cancer cells." (PMID 24736807, 2014). "The miR-17/20 cluster functions as a tumor suppressor in human breast cancer by decreasing AIB1 and cyclin D1 expression." (PMID 24658544, 2014). "These chromosomes contain genes that are commonly involved in the invasion, metastasis and pathogenesis of breast cancer, including c-MYC on 8q24; HRAS, CD151, CTSD on 11p15; CCND1 on 11q13; and TOP2A on 17q21." (PMID 24456987, 2014). "Inhibition of cyclin D1 or CDK4/6 increases or decreases migration and stem-like cell activity in ER-negative and -positive breast cancer, respectively." (PMID 25216351, 2014). "We found that expression levels of the known cell cycle-regulating miR-34 targets CCND1, CDK4 and CDK6, were downregulated upon miR-34c expression in breast cancer cell lines." (PMID 25064703, 2014). "Collectively these findings suggest that UBE2D3 participates in the process of hTERT-mediated radiosensitivity in human breast cancer MCF-7 cells by regulating hTERT and cyclin D1." (PMID 23741361, 2013). "CCND1 gene amplification was observed in 8.7% and RSF1 in 6.8% of these patients, preferentially in estrogen receptor-positive breast cancers." (PMID 24367492, 2013).
breast cancer (continued). "c-MYC protein was high in most TN breast cancer cell lines, including MDA-MB231 and MDA-MB468 as were levels of cyclin D1 in several TN breast cancer cell lines, including HCC38 and HCC1937." (PMID 24143235, 2013). "The significance of these three markers, cyclin D1, CDK4 and p16, for breast cancer and carcinogenesis is nevertheless still controversial." (PMID 23336272, 2013). "ZNF703 was recently identified as a novel breast cancer oncogene in the 15% of breast cancers that harbor 8p12 amplifications, amplified second only to the well-known oncogenes, ERBB2 and cyclin D1 (CCND1)." (PMID 23991038, 2013). "These probes were reported to enter breast cancer cells overexpressing IGF-1R and then hybridize specifically with CCND1 mRNA to produce strong xenograft tumor signals." (PMID 23533377, 2013). "The decreased expression of Wnt/β-Catenin targeting genes, such as cyclin D1, C-myc and survivin, and the inhibition of the activity of the transcription factor (T-cell factor 4, TCF-4) were observed in GL-treated breast cancer cells." (PMID 23914993, 2013). "Rab27A has effects on the invasive and metastatic potentials of breast cancer cells by modulating the secretion of IGF-II, which regulates the expression of p16, VEGF, uPA, cathepsin D, cyclin D1, and MMP-9." (PMID 23977139, 2013). "As has been said, all the factors studied here contribute to the RB pathway, and the aim was to reveal the significance of cyclin D1 and its regulators, CDK4 and p16, and their interrelations in human breast cancer." (PMID 23336272, 2013). "Accumulation or over-expression of cyclin D1 (CCND1) occurs in a majority of breast cancers and over-expression of CCND1 leads to accumulation of activated CCND1/CDK2 complexes in breast cancer cells." (PMID 23390492, 2013). "We also report that a highly specific AHR agonist significantly (P < 0.05) inhibits the expression of E2F1, CCND1 (known as Cyclin D1), MYB, SRC, JAK2, and JUND in breast cancer cells." (PMID 24171117, 2013). "It is known that amplifications of CCND1 and MYC frequently occur together in breast cancer; accordingly, we observed its down-regulation coupled with MYC down-regulation (logFC −1.2)." (PMID 23405235, 2013). "On the other hand, some genes that are described as recurrently amplified in human breast cancers were affected by losses in at least two tumors (e.g. EGFR, IGFR, and CCND1)." (PMID 24098698, 2013). "In conclusion, it appears that cyclin D1, CDK4 and p16 function independently in human breast cancer." (PMID 23336272, 2013). "Cyclin D1 and IGF -1R are the key regulators of cell proliferation that are overexpressed in most breast cancers." (PMID 22485142, 2012). "Our present data also suggested that AC-mediated inhibition of cyclin D1/E is directly proportional to the suppression of HER-2/neu and PI3K/Akt in human breast cancer cells." (PMID 22701509, 2012). "Gene copy number gain of CCND1, TRAF4, CDC6 and MTDH was seen in >40 % of the male breast cancer cases, with also frequent amplification." (PMID 22527098, 2012). "Recently, we reported that STAT5b regulates the transactivation of cyclin D1 and IGF-1 upon hypoxia stimulation in breast cancer cells." (PMID 22485142, 2012). "In this report anti-estrogen ICI 182780, shown to downregulate ER and cyclin D1, negates latent recurrence in MCF-7 breast cancer cells." (PMID 22860097, 2012). "As a continuation of our recent work, we investigated the expressions of cyclin D1 and p21 in NMU-induced breast cancer of Wistar Albino rats." (PMID 23508728, 2012).